CTLA4 (cytotoxic T-lymphocyte associated protein 4)
Diseases named in the same sentence as CTLA4 in open-access papers (continued):
Sharing a sentence is not in itself a finding about the gene and the disease.
melanoma (continued). "Besides, treatment with anti-CTLA-4 antibody ipilimumab has been shown to increase T cell infiltration into melanomas and broaden the TIL response to tumors." (PMID 33062726, 2020). "Thus, it was only a question of time until first clinical trials combined IDO inhibitors like epacadostat or navoximod with inhibitors targeting the PD-1/PD-L1 axis or CTLA-4 in differnt tumor entities, including advanced melanoma." (PMID 32117271, 2020). "MARCO is a scavenger receptor expressed on the surface of a group of suppressive TAMS, and a monoclonal antibody targeting it showed a response in breast and colorectal cancer, and melanoma models while facilitating the efficacy of anti-CTLA-4 antibody therapy." (PMID 35582437, 2020). "To test whether immune memory induced by ISV + α-CTLA-4 at an extracranial site was effective in preventing tumor engraftment in the brain, we engrafted mice with B78 melanoma on the right flank and rendered them disease free as above." (PMID 32690669, 2020). "The expression of CTLA-4 molecules on T cells is also often increased in melanoma and, as was mentioned before, may lead to T lymphocyte anergy." (PMID 33171792, 2020). "When CTLA-4 and PD-1 are co-blocked in B16 melanoma cells vaccinated with B16-Flt3-ligand (Fvax), these agents synergistically increase the ratio of Teff to Treg and myeloid-derived suppressor cells, as well as the production of T cells that secrete IFN-γ and TNF-alpha." (PMID 31968651, 2020). "Targeting BRAF (v-raf murine sarcoma viral oncogene homolog B1), MEK (mitogen-activated protein kinase), the immune checkpoint receptors cytotoxic T-lymphocyte-associated antigen 4 (CTLA-4), and programmed cell death PD-1 has improved the overall survival of melanoma patients." (PMID 32052079, 2020). "CTLA-4 and PD-L1 are known to be expressed on Tregs and melanoma cells." (PMID 32793206, 2020). "The distribution of memory versus non-memory cells in CD8 T cell populations has been associated to anti-CTLA4 therapy responses to but not to anti-PD-1 therapy in melanoma patients." (PMID 32244396, 2020). "Furthermore, an important role of INFγ in response to immunotherapy was supported by gene expression analyses in melanoma tumors before treatment with anti-CTLA-4 antibodies." (PMID 32517213, 2020). "When compared with homozygosity, heterozygosity at one HLA‐I locus could significantly enhance clinical outcomes in NSCLC or melanoma patients who received anti‐CTLA‐4 or anti‐PD‐1 therapies." (PMID 32997401, 2020). "This signature was associated with resistance to anti-PD-1, but not with anti-CTLA-4, in three additional melanoma cohorts and was also described in other tumor types, where its predictive value was however not proven." (PMID 32793228, 2020). "Moreover, sPD-L1 was also associated with a poor prognosis among patients treated with anti-CTLA4 for a melanoma, suggesting that the implications of this soluble biomarker extend beyond its interactions with mPD-1/PD-L1." (PMID 32085544, 2020). "Programmed cell death protein 1 (PD-1) and CTLA4 combination blockade enhances clinical efficacy in melanoma compared with targeting either checkpoint alone; however, clinical response improvement is coupled with increased risk of developing immune-related adverse events (irAE)." (PMID 33127658, 2020). "This association has also been observed in dacarbazine-experienced patients with melanoma treated with anti-CTLA4 ICB49, suggesting that tumor heterogeneity may be significantly correlated with ICB resistance." (PMID 31792460, 2019). "Likewise, samples from a mouse melanoma model exhibit reduced UPR in those that responded to anti-CTLA4 therapy." (PMID 30940817, 2019). "A recent study demonstrated that CAR-T cells transfected with siRNAs targeting PD-1 alone or in combination with siRNA targeting CTLA-4 produced more effector cytokines and showed a significant increase in cytotoxicity towards melanoma cells expressing PD-L1 as compared to control cells." (PMID 30717461, 2019).
melanoma (continued). "Moreover, melanomas are highly immunogenic tumors and checkpoint inhibitors have been very successful, with pembrolizumab superior to ipilimumab (which targets CTLA-4)." (PMID 31481958, 2019). "In a transplantable model of B16 melanoma cells the presence of microglia (CD11b+F4/80+CD45low) infiltration into intracranial B16 melanoma tumors increased following combined PD-1/CTLA-4 blockade and the increase in microglia correlated with intracranial therapeutic efficacy." (PMID 31481958, 2019). "Furthermore, nivolumab is shown to have a higher efficacy as compared to chemotherapy in patients with melanoma, who progressed after CTLA-4 treatment." (PMID 31134056, 2019). "UV mutation signature and overall mutation burden in melanoma patients confer clinical benefit to CTLA-4 inhibition, but not to adoptive cellular therapies." (PMID 31395100, 2019). "In the last few years systemic therapies have evolved; targeted therapies with BRAF and MEK inhibitors and immunotherapy with PD-1/PD-L1 or CTLA-4 checkpoint inhibitors, given alone or in combination, have significantly improved survival in patients with melanoma brain metastases." (PMID 30975225, 2019). "Melanoma patients largely comprise the anti-CTLA-4 group, and may have distinct demographic and toxicity proclivities compared with the more pan-tumor population treated with anti-PD-1/PD-L1." (PMID 31118078, 2019). "In order to better understand the significance of this low-level expression of PD-1 on these antigen-specific KLRG1hi CD8 T cells, we analyzed the co-expression of CTLA-4 as high levels of PD-1 and CTLA-4 on TIL have been shown to identify exhausted CD8+ T cells in melanoma." (PMID 30323352, 2019). "Ipilimumab and tremelimumab are two well-characterized anti-CTLA-4 antibodies, the first approved for treatment of malignant melanoma, colorectal cancer, and renal cell carcinoma and the second being tested in clinical trials on colorectal cancer and lung cancer patients." (PMID 31134056, 2019). "In addition to use as single agents, dual CTLA-4/PD-1 inhibiting regimens have been approved for melanoma and renal cell carcinoma." (PMID 31200747, 2019). "Finally, we show that by combining both an enhanced potency TLR9 agonist (MGN1703) and a depletion-optimized CTLA-4 antibody (9D9-mIgG2a), half of pre-implanted parental B16-F10 melanoma can be cured." (PMID 31771649, 2019). "However, CTLA-4-targeted therapy permanently altered the landscape for the treatment of melanoma, as well as several other aggressive malignancies." (PMID 31439034, 2019). "Particularly, strategies targeting immune checkpoint molecules through inhibition of programmed death 1 (PD-1) and cytotoxic T lymphocyte antigen-4 (CTLA-4) have demonstrated clinical benefit in several malignancies, such as melanoma, Hodgkin’s lymphoma, and non-small cell lung cancer (NSCLC)." (PMID 30987642, 2019). "Checkpoint inhibitors, which target the programmed cell death pathway (PD-1 and PD-L1) and the cytotoxic T-lymphocyte-associated antigen-4 (CTLA-4), are effective in the treatment of several types of cancers, including melanoma, RCC, and non-small cell lung cancer." (PMID 30828430, 2019). "In addition to this, IFNγ was recently described as an upregulator of CTLA-4 in melanoma cells, another long-established immune checkpoint inhibitor." (PMID 31779626, 2019). "The expression of CTLA-4 and PD-1 has been observed on lymphocytes of dogs with mastocytoma, melanoma, and renal cell carcinoma, and studies using a human monoclonal antibody against PD-L1 has confirmed expression of PD-L1 on a number of canine tumour biopsies." (PMID 30739231, 2019). "Immune checkpoint inhibitors directed against CTLA-4, PD-1 or PD-L1 have recently demonstrated a therapeutic benefit in various solid tumors (e.g., melanoma, head and neck squamous cell carcinoma, gastric cancer, colorectal cancer, NSCLC, etc.)and lymphoid malignancies." (PMID 30967859, 2019).
melanoma (continued). "Notably, a transient decrease in HIV RNA was observed in an HIV-infected patient being treated for melanoma after infusion of an anti-CTLA-4 antibody, ipilimumab." (PMID 31681335, 2019). "Based on these findings, we hypothesized that pre-existing antibodies against a broader range of antigens may correlate with clinical outcome of melanoma patients treated with therapies targeting PD-1/PD-L1 and CTLA4." (PMID 30786924, 2019). "Notably, broader clonal expansions of blood T cells before treatment predicted longer survival times of melanoma patients following CTLA4 inhibition and were also observed in long-term survivors from anti PD-1 therapy." (PMID 31275310, 2019). "A study investigated 64 patients with malignant melanoma treated with anti-CTLA4 antibodies." (PMID 31277279, 2019). "Hypotheses that CTLA-4 blockade could enhance anti-tumor response were tested by a pre- clinical study using transplantable murine melanoma cell lines, demonstrating that CTLA-4 inhibitors induced rejection of melanoma." (PMID 30941125, 2019). "Indeed, the absolute number of lymphocytes in blood samples correlates with clinical outcome in melanoma patients treated with ipilimumab, a monoclonal antibody targeting the co-inhibitory receptor CTLA-4." (PMID 31176366, 2019). "We then analyzed how CTLA4 blockade might affect TCR repertoires in the CD4+ and CD8+ T-cell subsets in 17 melanoma patients treated with CTLA4 antibody." (PMID 31275310, 2019). "A relevant breakthrough in melanoma has been obtained by immunotherapy combinations, revealing that the CTLA4 activation mostly occurs in lymph nodes while the modulation of T-cell functions by PD-1 stimulation has been mostly described in the microenvironment of peripheral tissues." (PMID 31750245, 2019). "For example, a study of patients with melanoma brain metastasis showed that concurrent immunotherapy with anti-PD-L1 and anti-CTLA-4 showed improved response rates if immunotherapy was given within a time frame of 4 weeks after radiation compared to treatments that were more than 4 weeks apart." (PMID 30941312, 2019). "On the contrary, immunotherapy using anti-PD-1/PD-L1 agents and anti-cytotoxic T-lymphocyte associated protein-4 (CTLA-4) have shown promising and encouraging results in other malignancies including melanoma, lung cancer, renal cell carcinoma, and bladder cancer." (PMID 31366113, 2019). "As a particular finding, the data obtained this way demonstrate that broader T-cell responses with a greater diversity of CD4+ blood T-cell clones may predict longer survival of melanoma patients treated with anti-CTLA4 or PD-1 antibodies." (PMID 31275310, 2019). "Indeed, pre-existing antibodies against the tumor antigen NY-ESO-1 in the serum of patients with melanoma correlate with an improved clinical benefit following anti-CTLA4 immunotherapy." (PMID 31086070, 2019). "Indeed, several studies have provided important insights for T-cell dynamics in blood of melanoma patients under CTLA4 blockade." (PMID 31275310, 2019). "Moreover, Veatch and colleagues recently identified HLA-DQB1*03-restricted BRAFV600E-specific CD4+ T cells in an acral melanoma patient, who nonetheless developed metastases under ipilimumab (anti-CTLA-4) immunotherapy." (PMID 31998317, 2019). "Whether there is a depletion or reduction of Treg cells in melanoma microenvironment as mechanism of therapeutic anti-CTLA-4 antibodies in the patients is still under debate." (PMID 31028434, 2019). "Moreover, combined regimen of nivolumab and ipilimumab, which acts by both inhibiting PD-1 and CTLA-4 has notable 55% CNS response in melanoma brain metastases patients." (PMID 32309611, 2019). "Anti–CTLA-4 mAb therapy has shown promise in several cancers, most notably in melanoma." (PMID 30975211, 2019).
melanoma (continued). "In order to determine which patients may respond best to checkpoint inhibition we retrospectively analyzed immune cell infiltration and PD-L1 status in a cohort of melanoma treated with CTLA-4 and/or anti-PD-1 inhibitors." (PMID 30931305, 2019). "Combination therapy blocking both CTLA-4 and PD-1 is now approved for melanoma." (PMID 31443741, 2019). "IC inhibitors targeting programmed cell death receptor 1 (PD-1) and its ligand (PD-L1), cytotoxic T lymphocyte-associated protein 4 (CTLA-4), and lymphocyte activation gene-3 (LAG-3) are over-expressed in several cancers, such as lung cancer, melanoma, and triple-negative breast cancer (TNBC)." (PMID 30506221, 2019). "Moreover, circulating serum PD-L1 was suggested to be a biomarker for predicting immune checkpoint inhibitor response, particularly to the blockade of PD-1 and CTLA-4 in malignant melanoma and multiple myeloma." (PMID 30872362, 2019). "Together, many different circulating clones, but not a few strongly expanded T-cell clones may favor the clinical responses to CTLA4 inhibition in melanoma patients." (PMID 31275310, 2019). "Interestingly, a recent research proved that CTLA-4 is also expressed on melanocytes and melanoma cells and it was regulated by IFN-γ, which is a potential strategy to cure melanoma." (PMID 31134073, 2019). "Studies using the murine B16.SIY melanoma mouse model have shown that combinations of CTLA-4 or PD-1/PD-L1 with IDO blockade restored both IL-2 production and CD8+ T cell proliferation within the TME, pointing to the potential merits of a combinational targeting approach." (PMID 30941125, 2019). "Furthermore, we observed a therapeutic effect of the combination treatment with anti-CTLA-4 and anti-PD-1 antibody against established B16 melanomas in the same mice." (PMID 31214189, 2019). "Anti-CTLA4 and anti-PD-1 therapies can prolong survival rates of patients with advanced melanoma, but also induce organ-specific toxicities in a substantial number of patients, termed immune-related adverse events (IrAEs), which restrict the long-term benefits from this immunotherapeutic approach." (PMID 31275310, 2019). "To further assess the effectiveness and robustness of pTuneos, we also applied the whole pipeline to three independent datasets comprising anti-CTLA-4-treated melanoma patients and anti-PD-1-treated lung cancer patients to compare the identified neoantigen profile with patient survival patterns." (PMID 31666118, 2019). "For example, the combination of moDCs with anti-CTLA4 blockade in advanced melanoma patients showed an encouraging response rate of 38%, with all complete responders (n = 7) still free from progression and off-therapy more than 5 years after the initiation of DC therapy." (PMID 30999964, 2019). "Similarly, among 57 patients with melanoma treated with CTLA4 blockade, significantly improved OS was observed in patients with tumors characterized by a high clonal neoantigen burden and low neoantigen ITH." (PMID 31277279, 2019). "Given toxicity of PD-1/PD-L1 blockade is drastically lower than that of anti-CTLA-4 antibodies in previous studies, it may achieve outstanding outcomes in melanoma patients when combined with MAPK inhibition." (PMID 31134073, 2019). "In naïve mice with B16-F10 melanoma tumors that received PD-L1 and Cytotoxic T lymphocyte-associated protein 4 (CTLA-4 or CD152) directed ICI therapy, high tracer uptake was observed in the tumor upon irradiation, suggesting that PD-1 PET can be used for ICI treatment monitoring." (PMID 31696402, 2019). "Monoclonal antibodies targeting the cytotoxic T-lymphocyte-associated antigen 4 (CTLA4) (e.g., ipilimumab [IPI]) and the programmed cell death-1 (PD1) receptor (e.g., nivolumab [NIVO]) represent significant breakthroughs in the treatment of advanced melanoma." (PMID 31312536, 2019).
melanoma (continued). "We sought to test whether activation of TLR9 through intra-tumoral injection in the B16-Ova melanoma model could potentiate systemic, sterilizing anti-tumor immunity in conjunction with blockade of the T cell immune checkpoint receptor CTLA-4." (PMID 31771649, 2019). "For patients with melanoma, this is anti-PD-1 instead of anti-CTLA-4 therapy." (PMID 30992053, 2019). "In the present study, we established a dextran sulfate sodium (DSS)-induced colitis and B16 melanoma tumor mouse model to imitate the clinical outcomes of patients receiving ipilimumab (Anti-CTLA-4) and nivolumab (anti-PD-1), for whom colitis is the most frequent problem encountered." (PMID 31214189, 2019). "Interestingly, men but not women showed a significant better OS when treated with anti-CTLA-4, with the exception of melanoma patients, with women showing a benefit as well." (PMID 30545122, 2018). "Analysis of peripheral blood of 59 melanoma patients treated with CTLA-4 inhibitor showed that the baseline monocytic MDSCs, neutrophils, and monocytes were more abundant in non-responders when compared to responders, which also experienced increased serum concentrations of MDSC attractants." (PMID 29482595, 2018). "Using a HuProt human proteome array, we profiled baseline antibody levels in sera from melanoma patients treated with anti-CTLA-4, anti-PD-1, or the combination, and used support vector machine models to identify pre-treatment antibody signatures that predict irAE development." (PMID 29606147, 2018). "Ipilimumab was the first anti- CTLA-4 antibody to be approved in advanced melanoma." (PMID 29946544, 2018). "Iannone and colleagues also found that blockade of CD73 could enhance efficacy of anti-CTLA-4 in melanoma model." (PMID 29514610, 2018). "Moreover, the anti-tumor effect seen in melanoma mouse models was enhanced by concomitant CTLA-4 and PD-L1 blockade." (PMID 30619273, 2018). "Our group recently demonstrated that the high levels of CD28 and PD-1 exposed by Exo correlate with the therapeutic response to anti-CTLA4 immunotherapy in metastatic melanoma, whereas those from DCs reflect the restoration of immune system activity against melanoma cells." (PMID 29755693, 2018). "NDV combined with CTLA-4 antibody was used to treat mouse B16 melanoma." (PMID 29857493, 2018). "Several immune checkpoint inhibitors, including antibodies against CTLA-4 and PD-1/PD-L1, have been approved for use in the clinic and have shown remarkable responses in the treatment of various cancers, including melanoma, non–small cell lung cancer and renal cell cancer." (PMID 29666167, 2018). "Current treatment strategies for high-stage melanoma are based around the use of immunotherapy with immune checkpoint inhibitors such as anti-PDL1 or anti-CTLA4 antibodies to stimulate anti-cancer T cell responses, yet a number of patients will relapse and die of disease." (PMID 29776373, 2018). "Quantitative real-time RT-PCR analyses were performed to study the effects of treatment with different DHAs on the expression levels of IC (i.e., CTLA-4, PD-1 and PD-L1) mRNA molecules, in IC-negative cancer cells, selected among the investigated 14 melanoma and 10 hematological cancer cell lines." (PMID 30581389, 2018). "Also other studies showed that treatment with attenuated viruses expressing blocking antibodies of CTLA-4 resulted in a delayed tumor growth and prolonged survival in murine models of both melanoma and lung cancer." (PMID 30619273, 2018). "The emergence of some novel therapies against melanoma such as genetically targeted therapies (e.g., BRAF inhibitors) and immunotherapies (e.g., PD-1/PD-L1 and CTLA-4 antibodies) has undoubtedly improved melanoma treatment, but the overall prognosis of patients remains poor." (PMID 29483938, 2018).